FOXM1 (forkhead box M1)
Diseases named in the same sentence as FOXM1 in open-access papers (continued):
Sharing a sentence is not in itself a finding about the gene and the disease.
gastric cancer (continued). "Simultaneously, overexpression of FOXM1 counteracted the inhibitory effects of miR-361-5p on chemoresistance of gastric cancer cells through activating autophagy, further certifying the targeting relationship between the two." (PMID 29435149, 2018). "In agreement, overexpression of FOXM1 is a potential prognostic marker and enhances chemoresistance for docetaxel in gastric cancer." (PMID 29180117, 2018). "FOXM1 overexpression has been documented to facilitate the migration and invasion of gastric cancer cells via induction of Cathepsin D." (PMID 30021604, 2018). "Functionally, knockdown of miR-612 reversed the tumor-suppressive activity of PAX8, which recapitulates the effect of FOXM1 overexpression on PAX8-overexpressing gastric cancer cells." (PMID 30021604, 2018). "The results showed that overexpression of FOXM1 significantly rescued gastric cancer cells from PAX8-mediated inhibition of cell migration and invasion." (PMID 30021604, 2018). "In this study, FOXM1 induces cell migration and invasion of gastric cancer by inducingCath-D expression." (PMID 28978107, 2017). "In the present study, we found that overexpression of FOXM1 prompted cell migration and invasion of gastric cancer, and increased the expression of Cathepsin D (Cath-D)." (PMID 28978107, 2017). "In conclusion, this study demonstrated that FOXM1 promotes gastric cancer cell migration and invasion by inducing Cath-D, and then Cath-D cleaves E-cadherin to induce EMT development." (PMID 28978107, 2017). "Based on results above, we further analyzed the expression of FOXM1 and Cath-D proteins in 20 cases of gastric cancer tissues using immunohistochemistry (IHC)." (PMID 28978107, 2017). "To explore the role and mechanisms of FOXM1 in the progression of gastric cancer, we knocked down and overexpressed FOXM1 using their vectors in both gastric cancer cell lines, SGC7901 and MKN28." (PMID 28978107, 2017). "In conclusion, this study demonstrated that FOXM1 promotes gastric cancer cell migration and invasion through inducing expression of Cath-D in gastric cancer." (PMID 28978107, 2017). "FoxM1 expression was also recently reported to be modulated by many other transcription factors, and Her2 reportedly upregulated FoxM1 expression in gastric cancer." (PMID 28148279, 2017). "To analyze the impact of FOXM1 on cell migration of both gastric cancer SGC7901, and MKN28 cell lines, we performed wound-healing assays." (PMID 28978107, 2017). "According to recent references, we assumed that FOXM1 plays a different role in the progression of gastric cancer in different contexts, and FOXM1 also exert diverse biological effects at different stages." (PMID 28978107, 2017). "Thus, FOXM1 may be also a risk factor in gastric cancer patients with radiation or chemotherapy." (PMID 28978107, 2017). "In this work, FOXM1-overexpression increased expression levels of Cath-D to decrease the expression of E-cadherinin gastric cancer cells." (PMID 28978107, 2017). "The results of qRT-PCR and IHC showed that the expression of miR-320a was decreased in gastric cancer samples and negatively correlated with FoxM1 expression." (PMID 27086911, 2016). "At the same sites, we observed strong P27KIP1 expression, the down-stream target of FoxM1, in the normal tissues and weak expression in the gastric cancer tissues." (PMID 27086911, 2016). "Another study performed by our laboratory showed that DIM enhances the antitumorigenic properties of paclitaxel through the Akt/forkhaed box protein M1 (FOXM1) signaling pathway in gastric cancer cells." (PMID 27447608, 2016). "Inhibition of miR-320a resulted in the increase of colonies in all three gastric cancer cell lines, while co-transfection of miR-320a inhibitors and FoxM1 siRNA almost recovered the number." (PMID 27086911, 2016). "Compared with normal human tissues, gastric cancer specimens showed significant inhibition of miR-320a expression and activation of FoxM1." (PMID 27086911, 2016).
gastric cancer (continued). "We have previously reported that FoxM1 is activated in gastric cancer and that it induces gastric cancer cell proliferation by the inhibition of P27KIP1." (PMID 27086911, 2016). "Luciferase assays indicate that miR-320a suppresses FoxM1 expression, and in vitro recovery tests using FoxM1 siRNA indicate miR-320a inhibits gastric cancer cell proliferation by suppressing activity in the FoxM1-P27KIP1 axis." (PMID 27086911, 2016). "With the transfection of miR-320a inhibitors, the FoxM1 expression increased with P27KIP1 inhibition in all the gastric cancer cell lines." (PMID 27086911, 2016). "The role of GPC3 in the progression of invasive tumors supports the consideration of drugs that interfere with MAPK/FoxM1 pathways for a subset of gastric cancer patients." (PMID 27259271, 2016). "In this study, we showed that miR-320a expression is decreased in human gastric cancer tissues and correlates inversely with expression of FoxM1, a key cell cycle regulator involved in gastric carcinoma." (PMID 27086911, 2016). "Altogether, our data have revealed a crucial role of miR-320a in limiting the gastric carcinoma by directly targeting FoxM1- P27KIP1 axis." (PMID 27086911, 2016). "We have previously found that gastric carcinoma samples have activated several signal pathways, including the Forkhead box M1 (FoxM1) signaling pathway, which includes special miR-320a." (PMID 27086911, 2016). "In this study, we aimed to identify the role of miR-320a in gastric carcinoma and the down-stream FoxM1 and P27KIP1 regulatory mechanisms both in vitro and in vivo." (PMID 27086911, 2016). "By analyzing the microarray data, we found that some important signaling pathways, such as NF-κB, Wnt/β-catenin, Ras-MAPK, and FoxM1 were activated in gastric carcinoma." (PMID 27086911, 2016). "Future work will focus on using gene expression array data to assess alternative FOXM1 targets and novel FOXM1 interactions in gastric cancer." (PMID 26576650, 2015). "It has been reported that FOXM1 is a direct target of hsa-miR-370, and it was shown that the mRNA level of miR-370 was decreased in gastric cancer samples compared to normal tissue." (PMID 26640950, 2015). "Our results are consistent with this and confirm the overexpression of both FOXM1 protein and mRNA in gastric cancer." (PMID 26576650, 2015). "FOXM1 is overexpressed in a large proportion of gastric carcinomas at the protein level and FOXM1 and PLK1 are concomitantly overexpressed at the mRNA level in this cancer type." (PMID 26576650, 2015). "In our previous studies, it was shown that DFOG-induced cell apoptotic death was mediated by the inactivation of FOXM1 in ovarian and gastric cancer cells." (PMID 24959264, 2014). "The expression of FOXM1 and Stathmin in human gastric cancer samples was analysed by immunohistochemical staining." (PMID 24628949, 2014). "In summary, FOXM1 is a critical mediator of docetaxel sensitivity and resistance in gastric cancer cells." (PMID 24628949, 2014). "As determined by Pearson*s correlation test, FOXM1 and Stathmin expression levels were positively correlated in those gastric cancer samples (P = 0.029)." (PMID 24628949, 2014). "FOXM1 and Stathmin showed overlapping expression in gastric cancer cells, among which, the expression of FOXM1 is located in the nucleus and cytoplasm of cells, while Stathmin protein mainly expressed in the cytoplasm." (PMID 24628949, 2014). "Although our study gave the evidence to the hypnosis that FOXM1 mediates resistance to docetaxel in gastric cancer and expounded the mechanism, the accurate binding sites at gene level were not revealed yet." (PMID 24628949, 2014). "Recent studies have demonstrated that FOXM1 overexpressed in gastric cancer and that elevated FOXM1 promoted tumour development in various kinds of cancers, correlated closely with poor outcome." (PMID 24628949, 2014).
gastric cancer (continued). "Consistently, the functions of Twist 1 on the expression levels of cell-cycle regulators were also reversed by FoxM1 siRNA oligos, suggesting that FoxM1 is required for the roles of Twist 1 in gastric cancer cells." (PMID 24204899, 2013). "Overall, IHC results revealed that the level of FOXM1 expression was significantly higher in gastric cancer than in para-cancer tissues (P < 0.001), indicating that FOXM1 was commonly overexpressed in human gastric cancers." (PMID 24004449, 2013). "In conclusion, our study showed that FOXM1 was an independent prognostic factor for gastric cancer patients." (PMID 24004449, 2013). "In current study, we examined the expression of FOXM1 protein in both gastric cancer specimens and cell lines, and assessed correlations among FOXM1 overexpression, clinic-pathological characteristics and clinic outcome." (PMID 24004449, 2013). "Our study demonstrated that the level of FOXM1 expression was significantly higher in gastric cancer than in para-cancer tissues (P < 0.001) and normal gastric cell lines (P = 0.026)." (PMID 24004449, 2013). "In the present study, we show that Twist 1 overexpression leads to a significant up-regulation of FoxM1, which plays a key role in cell cycle progression in gastric cancer cells." (PMID 24204899, 2013). "In current study, we demonstrated that the level of FOXM1 expression was significantly higher in gastric cancer than in para-cancer tissues and normal gastric cell lines." (PMID 24004449, 2013). "In conclusion, we here show that Twist 1 overexpression leads to a significant up-regulation of FoxM1, which plays a key role in cell cycle progression in gastric cancer cells." (PMID 24204899, 2013). "FOXM1 amplification was identified as an independent prognostic factor in gastric cancer (P = 0.001), and its affection is more significant in patients with tumor size larger than 5 cm (P = 0.004), pT3-4 (P = 0.003) or pIII-IV (P = 0.001)." (PMID 24004449, 2013). "FOXM1 was positively stained in the nuclei or cytoplasm of 79% gastric cancer cells, whereas the para-cancer tissues showed much lower levels of FOXM1 with nonspecific weak staining (11.8%)." (PMID 24004449, 2013). "Further, we also showed that FOXM1 is a critical mediator of docetaxel sensitivity and resistance in gastric cancer cells." (PMID 24004449, 2013). "In gastric cancer, FoxM1 expression is also up-regulated and its inhibition leads to cellular senescence, which is at least in part, dependent on p27 kip1." (PMID 24204899, 2013). "Taken together, shown by our research, the resistance of docetaxel is able to be reversed in gastric cancer cells through the inhibition of FOXM1." (PMID 24004449, 2013). "We examined the expression of FOXM1 in 103 postoperational gastric cancer tissues and 5 gastric cell lines by immunohistochemistry and western blot analysis respectively." (PMID 24004449, 2013). "It was demonstrated that FOXM1 overexpressed in gastric cancer and that elevated FOXM1 promoted tumor development in various kinds of cancers, correlated closely with poor outcome." (PMID 24004449, 2013). "Among the 103 gastric cancer specimens, 12 cases were detected as strongly positive for FOXM1 expression (12%), 38 cases were moderately positive (37%), 31 cases were weakly positive (30%), and 22 cases were negative (21%)." (PMID 24004449, 2013). "Its expression levels correlate with poor prognosis and metastasis in different tumors including gastric carcinoma, suggesting the possibility of using FoxM1 as a prognosis and/or diagnosis marker." (PMID 24204899, 2013). "For example, JAK/STAT3 inhibitors are under development and have shown early promise in gastric cancer patients, and FOXM1 inhibitors or cell cycle modulators could potentially be explored to specifically curb the proliferative drive in PGC." (PMID 40862793, 2025).
gastric cancer (continued). "For example, anti-silencing function 1B (ASF1B), a highly conserved histone chaperone protein, was found to interact with the transcription factor FOXM1 in gastric cancer cells, resulting in the increased enrichment of FOXM1 in PRDX3 promoter for PRDX3 transcription." (PMID 40227215, 2025). "The oncogenic transcription factor Foxm1 is highly expressed in gastric cancer tissues." (PMID 40548719, 2025). "Research revealed that overexpression of RNF112 could significantly elevate the ubiquitination level of FOXM1, resulting in FOXM1 degradation and thereby inhibiting the proliferation, invasion, and metastasis abilities of gastric cancer cells." (PMID 40514721, 2025). "For example, in gastric cancer, miR-877-5p is downregulated in gastric cancer tissues and inhibits the growth and cell cycle progression of gastric cancer cells and promotes apoptosis through targeting FOXM1." (PMID 38309290, 2024). "FOXM1 has, therefore, been identified as a potential therapeutic target for gastric cancer." (PMID 38014984, 2024). "FOXM1, a transcription activator pivotal for orchestrating the expression of cell cycle genes crucial in mitosis, has also been identified as an oncogenic factor, triggering DNA damage repair, proliferation and migration of gastric cancer cells." (PMID 39542983, 2024). "Additionally, a previous study using the TIMER deconvolution method found that FOXM1 expression is negatively correlated with CD8+ T cell infiltration in gastric cancer patients, corroborating our findings in EAC patients." (PMID 38373993, 2024). "FOXM1 then facilitates gastric cancer cell migration and invasion (8, –, 10)." (PMID 38014984, 2024). "FOXM1 exhibits inverse correlation with RNF112 in gastric cancer tissues." (PMID 37288663, 2023). "Notably, a marked inverse association between RNF112 and FOXM1 was noticed in gastric cancer compared with the other 32 tumor settings, indicating the RNF112/FOXM1 axis is relatively more important in gastric cancer." (PMID 37288663, 2023). "Furthermore, RNF112 was proven to serve as a tumor repressor by mediating the proteasomal degradation of FOXM1 and inhibiting its transcriptional network in gastric cancer." (PMID 37288663, 2023). "Interestingly, the expression of FOXM1 and SIRT7 is demonstrated to be correlated in gastric cancer, and FOXM1 deficiency downregulates SIRT7 in gastric cancer cells." (PMID 37957720, 2023). "RNF112-inhibited FOXM1 expression suppresses gastric cancer malignant behaviors in vivo." (PMID 37288663, 2023). "MiR-370 was reported to downregulate FOXM1 in gastric cancer." (PMID 37025658, 2023). "Screen for E3 ligase targeting FOXM1 degradation in gastric cancer." (PMID 37288663, 2023). "Although several E3 ubiquitin ligases targeting FOXM1 have been reported, further investigation is required to explore the prospect of FOXM1 as an anticancer target in gastric cancer, particularly with respect to its degradation via the ubiquitin-proteasome system." (PMID 37288663, 2023). "RNF112 suppresses FOXM1 protein expression and stability in gastric cancer." (PMID 37288663, 2023). "Importantly, FOXM1 overexpression is correlated with cisplatin resistance in breast 88 and ovarian cancer 89 as well as docetaxel chemoresistance in gastric cancer." (PMID 35910798, 2022). "Furthermore, the expression of FOXM1 has been negatively correlated with patient prognosis in gastric cancer." (PMID 36291811, 2022). "Similarly, both FoxM1 and FoxP3 were strongly expressed in gastric cancer, resulting in tumor metastasis, immune escape, and poor prognosis." (PMID 36301031, 2022). "In some studies, GPC3 was absent in invasive tumors and metastatic lymph nodes, and the presence of GPC3 causes downregulation of MAPK/FOXM1 (mitogen-activated protein kinase/forkhead box M1) signaling, which reduces the survival rate of gastric cancer patients." (PMID 35050429, 2022). "FOXM1 also promoted progression of gastric cancer by synergistically with PLAU." (PMID 35756697, 2022).
gastric cancer (continued). "In gastric cancer, FoxM1 targets transcription and activation of Prx3, promotes stemness and metabolic reprogramming of gastric cancer cells, and increases the expression of mitochondrial fatty acid oxidative phosphorylation rather than glycolysis, which promotes drug resistance of tumor cells." (PMID 35022030, 2022). "have found that FOXM1 is a downstream target gene of miR-877-5p in gastric cancer." (PMID 34124974, 2021). "Moreover, PVT1 can regulate forkhead box M1 (FOXM1) to facilitate gastric cancer growth and invasion." (PMID 32156248, 2021). "miR-194-5p inhibits epithelial and mesenchymal metastasis of gastric cancer by targeting FOXM1." (PMID 35008751, 2021). "The co-presence of both MET and FOXM1 is common in patients with gastric cancer." (PMID 33937262, 2021). "By driving the synthesis of SCF components (SKP2 and CKS1), FOXM1 initiates its own destruction, as 2 different SCF complexes, SCFFBXL2 and SCFFBXO31, target FOXM1 for degradation, with SCFFBXO31 specifically targeting FOXM1 at the G2/M boundary and SCFFBXL2 targeting FOXM1 in gastric cancer cells." (PMID 32805721, 2020). "The PLAU (plasminogen activator urokinase) protein has been shown to mediate the Treg suppressor function via STAT5 and ERK signaling pathways and could provide certain help for future treatment in gastric cancer together with FOXM1." (PMID 33718118, 2020). "Interestingly, unlike its tumor-suppressive role in colorectal cancer and HCC, PDEF is overexpressed in gastric cancer and promotes gastric cancer cell proliferation by regulating FoxM1 expression through a positive feedback loop." (PMID 33585247, 2020). "Whether FOXM1/MET overexpression have any association with metastasis of PDA need to be validated, however, its role in lymph node metastases of gastric cancer has already been established." (PMID 33680951, 2020). "As a conclusion, the predicted inhibitors which could reverse the gene expression pattern in the different FOXM1/PLAU status groups may serve as potential therapeutic options in the gastric cancer in the future." (PMID 31949481, 2020). "PVT1 could interact with FOXM1 directly and increase its protein expression in gastric cancer and increased glucose uptake, lactate production, and the expression of HK2 in osteosarcoma cancer." (PMID 30083911, 2019). "Overexpressed FOXM1 enhanced autophagy and chemoresistance to docetaxel of GC cells, suggesting that overexpression of FOXM1 weakened the inhibitory effects of miR-361-5p on autophagy-induced chemoresistance in gastric cancer cells." (PMID 29435149, 2018). "Overexpression of FOXM1 has been reported to promote gastric cancer cell invasion." (PMID 30021604, 2018). "In the study of FoxM1 in gastric cancer, FoxM1 could inhibit cell apoptosis and promote proliferation of gastric cells." (PMID 29554906, 2018). "Knockdown of FOXM1 increases the sensitivity of gastric cancer cells to cisplatin." (PMID 30021604, 2018). "Interestingly, the lncRNA PVT1 can bind to FOXM1 protein and elevate its levels by reducing its degradation and enhancing its stability, subsequently promoting the proliferation and invasion of gastric cancer cells." (PMID 30208972, 2018). "Moreover, knockdown of miR-612 or overexpression of FOXM1 restored the angiogenic activity of gastric cancer cells with stable expression of PAX8." (PMID 30021604, 2018). "Moreover, FOXM1 is overexpressed in gastric cancer, and its inhibition leads to cellular senescence." (PMID 29180117, 2018). "Furthermore, enforced expression of FOXM1 reversed the anti-invasive activity of PAX8 in gastric cancer cells." (PMID 30021604, 2018). "Similarly, enforced expression of FOXM1 restored the aggressive phenotype of gastric cancer cells with miR-612 overexpression." (PMID 30021604, 2018). "Therefore, we provide evidence that PAX8-mediated reduction of FOXM1 in gastric cancer cells is ascribed to induction of miR-612." (PMID 30021604, 2018).